APP (amyloid beta precursor protein)
Diseases named in the same sentence as APP in open-access papers (continued):
Sharing a sentence is not in itself a finding about the gene and the disease.
neurodegenerative disease (278 papers, 2007 to 2026). A disorder of the central nervous system characterized by gradual and progressive loss of neural tissue and neurologic function. "In this study, we observed distinct splicing changes in Exon 8 of the APP gene, which has been implicated in neurodegenerative diseases." (PMID 40288647, 2025). "Yet another identified indirect interaction between COMT and SPINT2 was mediated via APP, protein associated with occurrence of neurodegenerative diseases such as Alzheimer disease." (PMID 36690660, 2023). "Other than the main effects of sleep deprivation on immune‐system function, plasma proteins associated with neurodegenerative diseases (APP, NOTCH3, SNCA, SOD1) were decreased after sleep deprivation, while only ATF6 continued to increase." (PMID 37139463, 2023). "Instead, NDR1/2 KO brains had significant increases in proteins associated with human neurodegenerative diseases (e.g., ApoE, Htt, APP, and PRNP), highlighting similarities between this mouse model and human disorders." (PMID 36446521, 2023). "Sorting Nexins (SNX) are important for correct intracellular transport including APP and AP-cleaving enzymes, dysregulation of which causes neurodegenerative disease." (PMID 35692428, 2022). "This is further substantiated by the evidence that increased LDL and total cholesterol levels are associated with increased risk for neurodegenerative diseases, amyloid precursor protein (APP) deposits, and amyloid-β (Aβ) peptide accumulation." (PMID 35625650, 2022). "This is illustrated by the association of APP to both neurogenesis and neurodegenerative diseases as well as the correlation of ANGPT1 with both ROP and diabetic retinopathy." (PMID 33895781, 2022). "Other neurodegenerative disease-linked proteins such as amyloid-precursor protein (APP) have also been shown to impede protein import following accumulation on the OMM and obstruction of the TOM40 subunit, behaving similarly to alpha-synuclein." (PMID 36090250, 2022). "Study of genetically modified mice has contributed to our understanding of the susceptibility to AD and other neurodegenerative diseases conferred by mutations or variants in APP, APOE, and related genes." (PMID 32580938, 2020). "In this regard, major proteins implicated in neurodegenerative diseases such as the amyloid precursor protein (APP), tau and alpha-synuclein and tau have been shown to be involved in metal ion processing and transport." (PMID 31644557, 2019). "No additional pathogenic mutations were found in other dominant causative genes of AD, FTD, or of other neurodegenerative diseases, such as APP, PSEN2, PRNP, PGRN, or MAPT." (PMID 30917570, 2019). "About half of the neurodegenerative disease-associated genes, namely APP, PSEN1, and PSEN2 for AD; C9orf72 and MAPT for FTD and SNCA; and PRKN and PARK7 for PD, have larger number of DPI robust TSSs than annotated CAT CAGE clusters." (PMID 30610612, 2019). "EVs can be implicated in neurodegenerative diseases also because they can deliver toxic proteins such as prions (PrPsc), alpha-synuclein, amyloid precursor protein (APP) or β-amyloid peptides, phosphorylated Tau, and SOD1." (PMID 26583089, 2015). "Several proteins associated with neurodegenerative diseases accumulate in brain following nbTBI, including α-synuclein, tau, the amyloid precursor protein (APP), and its product the β-amyloid (Aβ) protein." (PMID 23267342, 2012). "Our laboratory recently identified a fully functional IRE within the 5-UTRs of mRNAs implicated in neurodegenerative diseases, such as that of the amyloid-precursor protein (APP), associated with AD." (PMID 19399246, 2009). "Interestingly, AAV5-hRORA treatment attenuated accumulation of both A2E, the phototransduction waste product that damages RPE cells, as well as APP, the precursor to amyloid-β implicated in pathogenesis in retinal and neurodegenerative diseases." (PMID 38755404, 2024).
neurodegenerative disease (continued). "Another possibility is that aggregation-prone proteins, such as those variants implicated in neurodegenerative disease (amyloid precursor protein (APP), alpha-synuclein, Huntingtin, and Tau) associate with the import machinery and perturb the transport process." (PMID 38307874, 2024). "We saw that these genes of interest could be linked to known familial neurodegenerative disease genes (APP and HTT), and AD risk genes (APOE and PLCG2) from prior experimental studies using the Ingenuity database." (PMID 39231932, 2024). "Overall, our results suggest strongly that US9 can serve as a molecular driver that targets functional cargos to the APP machinery and can be used as a tool to study the contribution of lipid rafts to neurodegenerative disease conditions where amyloidogenesis has been implicated." (PMID 29118375, 2017). "Thus, inherited mutations that alter APP processing by either γ- or β-secretases provoke, with 100% penetrance, familial forms of neurodegenative diseases characterized by memory loss." (PMID 25247712, 2014). "It has also been established that APP and its degradation products localise to neuritic vesicles in the axons of AD brains, along with other neurodegenerative diseases, suggesting that APP accumulation may represent a hallmark of axonal injury." (PMID 24416616, 2013). "Here, we detected the altered level of GGA1, a Golgi protein that controls APP processing and Golgi alterations, suggesting that Aβ accumulation (a known hallmark in different neurodegenerative diseases) might be involved in cellular perturbations in DNAJC3mutcells." (PMID 34692675, 2021). "In particular, the progressive accumulation of misfolded proteins such as tau, amyloid precursor protein (APP), and α‐synuclein caused by dysregulation of RQC initiates UPRmt and elicits cellular stress in neurodegenerative diseases." (PMID 39668579, 2025). "In the context of neurodegenerative diseases, HS accumulation in the brain has been shown to bind amyloid precursor protein (APP), amyloid-β (Aβ), and tau protein, thereby promoting Aβ and tau aggregation." (PMID 41154677, 2025). "Some of these regions were linked to known PD or neurodegenerative disease risk genes, including SNCA, MAPT, PRKN, DJ-1 and amyloid precursor protein (APP)." (PMID 38892355, 2024). "This review elucidates the critical link between neurodegenerative diseases and specific posttranslational modifications, focusing on Tau, APP, α‐synuclein, Huntingtin protein, Parkin, DJ‐1, and Drp1." (PMID 39105197, 2024). "In contrast, the human CBL and PFC both display a significant upregulation of genes related to Amyloid protein production (APP), a major component of many neurodegenerative diseases with functions in synaptic signaling." (PMID 38275218, 2024). "We found three clusters defined mainly by genetic variants found in MAPT, APP, and APOE, considering known variants associated with AD and other neurodegenerative disease genetic architectures." (PMID 38693203, 2024). "BACE-1 is an important enzyme involved in APP processing and amyloid-peptide generation that contributes to the progression of neurodegenerative diseases." (PMID 37397495, 2023). "Interestingly, it was reported that thyroid hormones affect the expression of APP; meanwhile, their deficiency was accompanied by a significantly upregulated expression of the APP mRNA which in turn led to the accumulation of Aβ and tau protein and eventually brain degeneration." (PMID 37368180, 2023). "Several cytokines released in neurodegenerative diseases have been shown to upregulate the production of amyloid β protein precursor (APP) and neurotoxic amyloid β (Aβ) peptides in reactive astrocytes." (PMID 37513235, 2023). "Identification of genes, like APP, responsible for genetic forms of neurodegenerative diseases in human patients has provided important insights into the mechanisms require to maintain neuronal function and viability with age." (PMID 37923712, 2023).
neurodegenerative disease (continued). "TNTs have been proposed to play a key role in neurodegenerative diseases and are involved in the spread of aggregated proteins such as tau, APP, and huntingtin by an intracellular pathway instead of a soluble-mediated mechanism." (PMID 37396786, 2023). "Despite of the central pathological roles of aberrant APP processing in neurodegenerative diseases, APPs also play crucial physiological roles in brain development." (PMID 37387352, 2023). "In neurodegenerative diseases such as AD, the activation of GSK3α not only participates in the process of APP hydrolysis to form Aβ but also regulates the phosphorylation of tau." (PMID 36533181, 2022). "AD is a neurodegenerative disease characterized by the presence of Aβ plaques, which are extracellular aggregates of misfolded amyloid precursor protein (APP) and NFTs." (PMID 36361741, 2022). "In neurodegenerative diseases, such as AD, RAGE upregulation has been implicated in the stimulation of neuronal APP expression, and APP has been demonstrated to induce microglial activation accompanied by an increased inducible NO synthase expression." (PMID 36076994, 2022). "The shift of APP processing towards the amyloidogenic pathway and the formation of Aβ, as well as full-length APP, can be a link between cardiovascular and neurodegenerative diseases." (PMID 36289917, 2022). "Knowledge of the mechanisms of anterograde transport of APP and BACE1 is also relevant for the understanding the molecular basis of dysfunctional trafficking associated with neurodegenerative diseases." (PMID 35076977, 2022). "Among them, APP is a well-known gene involved in neurodegenerative diseases, whose 3′-UTR contains a target sequence of miR-130a-3p." (PMID 34413720, 2021). "Another mediator between HMGB1 and APP was receptor for advanced glycation end products (RAGE), which has been implicated in various neurodegenerative diseases, such as AD." (PMID 33946401, 2021). "APP is a well-characterized marker to detect axonal injury in neurodegenerative diseases such as MS." (PMID 34502405, 2021). "Previous studies have described the up-regulation of certain genes involved in neurodegenerative diseases including amyloid precursor protein (APP), ubiquilins (UBQLN) and Jun proto-oncogene (JUN) as candidate genes for NAFLD." (PMID 34565410, 2021). "Previous studies have mainly focused on the role of NLRP3 inflammasome in microglia as well as its effects on neurodegenerative diseases in APP/PS1 mice and in humans." (PMID 34924922, 2021). "Clearly, more longitudinal studies are needed to confirm the predictive value of δ-secretase-generated tau, APP and other fragments for the early diagnosis of AD and other neurodegenerative diseases." (PMID 31911834, 2020). "Contrary to the expression of these genes in neurodegenerative diseases, we reported a decreased expression of APP and the UPR indicative genes." (PMID 33066537, 2020). "Even if APP is notoriously known for its contribution to pathogenesis of neurodegenerative diseases, and many physiological roles have been identified in neural cells, little is known on its function on endothelial cells and cerebral vasculature." (PMID 32973564, 2020). "Because δ-secretase simultaneously cleaves both APP and Tau, it provides an unprecedent innovative target for treating this devastating neurodegenerative disease." (PMID 31911834, 2020). "Although not specific for ALS, some studies support a role for Aβ1-42 and amyloid precursor protein (APP) in the pathogenesis of neurodegenerative diseases than other AD, such as ALS." (PMID 32326346, 2020). "Overproduction and accumulation of beta amyloid peptide (Aβ)—formed from the larger amyloid precursor protein (APP)—plays an important role in the pathogenesis of this neurodegenerative disease." (PMID 32785075, 2020).
neurodegenerative disease (continued). "δ-Secretase cleaves key regulators of neurodegenerative diseases such as APP, tau, α-synuclein, SET, and TDP-43, and plays a pivotal role in the pathogenesis of AD, PD, and FTD/ALS." (PMID 31911834, 2020). "While the etiology and epidemiology of AD and NPC differ, these neurodegenerative diseases share many disease-related molecular pathways, including cholesterol accumulation, lysosomal abnormalities, tau hyperphosphorylation, APP processing and Aβ deposition." (PMID 31902793, 2020). "In contrast, studies done in APP/PS1 mice show that insulin sensitivity improves autophagy in neurodegenerative disease models." (PMID 31427921, 2019). "We demonstrate that HARDEN can be applied to the neurodegenerative disease genes C9orf72 and APP, and methylation can be induced via HDR with both single and double stranded methylated repair templates." (PMID 31680172, 2019). "We also demonstrate that HARDEN is not specific to the C9orf72 locus, but can be used to methylate the neurodegenerative disease gene APP as well." (PMID 31680172, 2019). "Evaluation of a marker for neurotoxicity, APP, a precursor for Amyloid β that accumulates extracellularly in neurodegenerative diseases such as Alzheimer’s, indicated dose-and time dependent effects of the two types of dust." (PMID 30654492, 2019). "The APP molecule that is produced during brain degeneration as well as the products of inflammatory reaction are reported to be directly associated with deficits in social interaction, memory loss, and behavior." (PMID 31248209, 2019). "Further studies will be required to address the exact means whereby BHD regulates APP processing and protects against neurodegenerative diseases." (PMID 30645580, 2019). "Important proteins that are involved in the formation of neurodegenerative diseases include cuproproteins such as the amyloid precursor protein (APP) and prion protein (PrP)." (PMID 30621285, 2019). "This suggests that very likely, APP and GDNF are linked in different neurodegenerative diseases but the mechanistic aspects are peculiar to the specific disease and still need to be decipher." (PMID 29899726, 2018). "BRI2 is a relevant protein in the pathogenesis of the neurodegenerative diseases FBD and FDD, as well as in AD, given its association with APP and its effects on Abeta production, aggregation and degradation." (PMID 29476059, 2018). "Reduction in amyloid beta deposition by activation of p-AMPK influencing APP processing genes makes osmotin a potent therapeutic candidate for neurodegenerative diseases." (PMID 28811634, 2017). "Given the implications of APP mRNA downregulation for neurodegenerative disease mechanisms, we used immunoblotting to examine APP protein expression in whole cell lysates from hNP1 cells harvested after 12 days in differentiation medium." (PMID 28913617, 2017). "Thereby it highlights the importance of the localization of APP processing and intracellular transport as a decisive factor for mitochondrial function, linking two prominent hallmarks of neurodegenerative diseases." (PMID 28005987, 2016). "Other proteins central to neurodegenerative diseases, such as APP, presenilin, and tau in AD are also substrates for caspase-6." (PMID 26505998, 2015). "Alpha-synuclein (Snca), the most important protein in this study, is aprotein whose accumulation is common to many neurodegenerative diseases, and it is non-Aβ component in AD amyloid that modulates the APP mRNA." (PMID 25561935, 2015). "It is widely accepted that changes in the interplay between APP, Aβ and mitochondrial function are likely to correlate with the onset of neurodegenerative diseases." (PMID 26834621, 2015). "We provide further evidence that Hirano bodies have a specific effect on the pathogenesis of neurodegenerative disease, with respect to tau and C-terminal fragments of APP." (PMID 24929931, 2014).
neurodegenerative disease (continued). "YY1 is a ubiquitous transcription factor previously noted to regulate several genes associated with neurodegenerative diseases including BACE1 and APP, SNCA, EAAT2, MTOR and PPARGC1A." (PMID 25187168, 2014). "Since tau co-localized with Hirano bodies and tau exhibits pathology in neurodegenerative diseases, we have studied the effect of tau in the presence of APP, AICDc58, and c31 and model Hirano bodies." (PMID 23028730, 2012). "Elucidating the function of APP should help understand AD pathogenesis and provide insights into therapeutic designs against this devastating neurodegenerative disease." (PMID 18070361, 2007). "Such a phenomenon could potentially occur with aging, physiological stress or neurodegenerative disease, potentially contributing to the accumulation of APP fragments and exacerbating disease progression." (PMID 40671818, 2025). "Antisense oligonucleotides (ASOs) have shown promise in reducing amyloid precursor protein (APP) levels in neurons, but their effects in astrocytes, key contributors to neurodegenerative diseases, remain unclear." (PMID 39877983, 2025). "Given the established role of lysosomal dysfunction in AD and other neurodegenerative diseases, this finding suggests that even subtle changes in lysosomal pH could significantly alter or impair APP clearance." (PMID 40671818, 2025). "Importantly, both enzymes are implicated in the processing of aggregate-prone proteins such as amyloid-beta precursor protein, linking them to the pathogenesis of neurodegenerative diseases." (PMID 40883786, 2025). "The most well-known neurodegenerative disease with pathogenesis is centered on excessive amyloid-beta precursor protein gene (APP) on chromosome 21 and the beta-amyloid cascade hypothesis." (PMID 40904616, 2025). "As for the other neurodegenerative diseases, familial forms (FAD) account for only a minority of cases and the most common mutations are found in presenilin 1 (PSEN1), presenilin 2 (PSEN2), and the amyloid precursor protein (APP)." (PMID 39273694, 2024). "The physiological regulation of APP and α-synuclein on mitochondria remains unclear, let alone whether they share common regulatory mechanisms affecting the development of neurodegenerative diseases." (PMID 37179386, 2023). "Future investigations of the physiological roles of APP and its interactors would lead to a better understanding of their relationships with neurodegenerative diseases and would provide important information to facilitate the development of effective therapeutic interventions for these diseases." (PMID 37387352, 2023). "In recent years, a growing number of studies have shown that miRNAs play a key role in the development of many neurodegenerative diseases, and their role in the pathogenesis of AD involves the regulation of amyloid precursor protein (APP), BACE1, neuronal apoptosis and other factors." (PMID 36875663, 2023). "However, the normal function of APP and the importance of that role in neurodegenerative disease is less clear." (PMID 37923712, 2023). "As AD is a slow progressing neurodegenerative disease, we performed our unbiased transcriptomic analysis of the brain endothelium in 1 year old female APP/PS1 mice as the increased Aβ deposition by this age would likely induce gene expression changes in the brain endothelium." (PMID 36182964, 2022). "Moreover, DYRK1A phosphorylates several neurodegenerative disease (NDD)-associated proteins, including tau, amyloid precursor protein (APP), and α-synuclein, affecting the formation of toxic protein inclusions in AD and PD." (PMID 33380426, 2021). "Also, TNT have been proposed to play a key role in neurodegenerative diseases involved with the spread of aggregated proteins such as tau, APP, and Huntington by an intracellular pathway instead of a soluble mediated mechanism." (PMID 34267246, 2021).